IDS (iduronate 2-sulfatase)
Diseases named in the same sentence as IDS in open-access papers (continued):
Sharing a sentence is not in itself a finding about the gene and the disease.
lysosomal storage disease (50 papers, 2011 to 2026). A metabolic disorder caused by mutations in proteins critical for lysosomal function, including lysosomal enzymes, lysosomal integral membrane proteins, and proteins involved in the post-translational modification and trafficking of lysosomal proteins. "Mucopolysaccharidosis II (MPS II) is a rare, life-limiting lysosomal storage disease caused by deficient iduronate-2-sulfatase activity." (PMID 40598289, 2025). "Mucopolysaccharidosis type II (MPS II), or Hunter syndrome, is a lysosomal storage disorder in which deficiency or inactivity of the enzyme iduronate-2-sulfatase leads to accumulation of glycosaminoglycans throughout the body." (PMID 41189009, 2025). "Mucopolysaccharidosis II (MPS II) is a rare lysosomal storage disease characterized by iduronate-2-sulfatase gene (IDS) deficiency and downstream glycosaminoglycan accumulation." (PMID 38610004, 2024). "Mucopolysaccharidosis II (MPS II; Hunter syndrome, OMIM 309900) is a rare, X-linked recessive, lysosomal storage disease characterized by deficient activity of the iduronate-2-sulfatase gene (IDS) and downstream glycosaminoglycan (GAG) accumulation." (PMID 38610004, 2024). "Mucopolysaccharidosis (MPS) II (Hunter syndrome; OMIM 309900) is a rare, X-linked, recessive lysosomal storage disease caused by pathogenic variants of the iduronate-2-sulfatase gene (IDS)." (PMID 37974184, 2023). "Mucopolysaccharidosis type II (MPSII) is a rare pediatric lysosomal storage disorder (LSD) caused by iduronate-2-sulfatase (IDS) enzyme deficiency due to mutations in the IDS gene (GenBank: NM_000202)." (PMID 37920237, 2023). "Mucopolysaccharidosis II (MPS II; Hunter syndrome; OMIM 309900) is a rare lysosomal storage disease caused by deletion or pathogenic variants of the iduronate-2-sulfatase gene (IDS)." (PMID 35961250, 2022). "Mucopolysaccharidosis type II (MPS II) is a lysosomal storage disorder based on a mutation in the IDS gene that encodes iduronate 2-sulphatase." (PMID 34070997, 2021). "Mucopolysaccharidosis II (MPS II; Hunter syndrome) is a rare, life-limiting lysosomal storage disease caused by deficient iduronate-2-sulfatase activity." (PMID 34717704, 2021). "Severe mucopolysaccharidosis type II (MPS II) is a progressive lysosomal storage disease caused by mutations in the IDS gene, leading to a deficiency in the iduronate-2-sulfatase enzyme that is involved in heparan sulphate and dermatan sulphate catabolism." (PMID 28207863, 2017). "Mucopolysaccharidosis type II (MPSII) is a lysosomal storage disorder due to the deficit of the iduronate 2-sulfatase (IDS) enzyme, causing progressive neurodegeneration in patients." (PMID 27512952, 2016). "This disorder belongs to the group of lysosomal storage disorders (LSDs) and is caused by a deficiency in the lysosomal enzyme iduronate 2-sulfatase (IDS; EC 3.1.6.13), which catalyzes the hydrolysis of 2-sulfate groups of dermatan sulfate (DS) and heparan sulfate (HS)." (PMID 38542525, 2024). "Conjugation of TfR mAbs with enzymes (e.g., β galactosidase-1, iduronate-2-sulfatase) has been investigated for their use in enzyme replacement therapy in lysosomal disorders (e.g., Niemann-Pick disease)." (PMID 39118806, 2024). "Deficiency of iduronate 2-sulfatase (IDS) causes Mucopolysaccharidosis type II (MPS II), a lysosomal storage disorder characterized by systemic accumulation of glycosaminoglycans (GAGs), leading to a devastating cognitive decline and life-threatening respiratory and cardiac complications." (PMID 38085235, 2024).
mucopolysaccharidosis (10 papers, 2020 to 2025). A group of autosomal recessive or X-linked inherited lysosomal storage disorders affecting the metabolism of mucopolysaccharides, resulting in the accumulation of mucopolysaccharides in the body. "Mucopolysaccharidosis (MPS) type II is caused by a deficiency of iduronate-2-sulfatase and is characterized by the accumulation of glycosaminoglycans (GAGs)." (PMID 38684682, 2024). "A decrease in two lysosomal enzymes, N-acetylgalactosamine-6-sulfatase (GALNS) and iduronate-2-sulfatase (IDS) could cause diseases of mucopolysaccharidoses: Morquio A syndrome and Hunter disease, respectively." (PMID 36080188, 2022). "Beyond sphingolipid/ceramide metabolism, our screen also identifies many fly homologs of genes causing human mucopolysaccharidoses (e.g., GLB1, IDS, IDUA, MAN2B1, MANBA)." (PMID 37200393, 2023). "We recently developed a blood–brain barrier (BBB)-penetrating enzyme transport vehicle (ETV) fused to the lysosomal enzyme iduronate 2-sulfatase (ETV:IDS) and demonstrated its ability to reduce glycosaminoglycan (GAG) accumulation in the brains of a mouse model of mucopolysaccharidosis (MPS) II." (PMID 32751752, 2020).
X-linked recessive disease (4 papers, 2011 to 2021). X-linked recessive form of disease. "It is an X-linked recessive disease caused by the deficit of the lysosomal hydrolase iduronate 2-sulfatase (IDS, EC3.1.6.13) involved in the catabolism of two mucopolysaccharides (or glycosaminoglycans, GAGs), heparan- and dermatan-sulfate." (PMID 28513549, 2017). "Mucopolysaccharidosis type II (MPS II) is a rare, life-limiting, X-linked recessive disease characterised by deficiency of the lysosomal enzyme iduronate-2-sulfatase." (PMID 22059643, 2011).
Cognitive impairment (3 papers, 2017 to 2025). Abnormal cognition is characterized by deficits in thinking, reasoning, or remembering. "In this study, there seemed to be no relation between the severity of the cognitive impairment and the concentration of the glycosaminoglycan excretion and plasma iduronate-2-sulfatase assay." (PMID 28077157, 2017).
hemophilia B (3 papers, 2018 to 2020). Hemophilia B is a form of hemophilia characterized by spontaneous or prolonged hemorrhages due to factor IX deficiency. "Of these initial gene sets, replacement of Factor IX, α-l-Iduronidase, and Iduronate-2 sulfatase for hemophilia B, MPS I and II have advanced to clinical trials." (PMID 32207531, 2020). "Our patient was diagnosed with mild hemophilia B after finding an 11 Mb deletion of Xq26.3q28 that included the following genes among others IDS,SOX3,FMR1,AFF2, and F9." (PMID 30264515, 2018).
X-linked disease (3 papers, 2013 to 2024). X-linked form of disease. "MPS II is a rare X-linked genetic disease caused by mutations in the IDS gene encoding iduronate 2-sulfatase (I2S)." (PMID 31071499, 2019). "Mucopolysaccharidosis type II (MPS II) is an inherited X-linked disease associated with a deficiency in the enzyme iduronate 2-sulfatase due to iduronate 2-sulfatase gene (IDS) mutations." (PMID 23800320, 2013).
cognitive decline (2 papers, 2022 to 2024). "We further found that three proteins, i.e., IDS, FHR1, and PGS1, were independently associated with faster global cognitive decline even after considering the presence of AD in the models." (PMID 35326481, 2022).
Lysosomal disease (2 papers, 2018 to 2022). "In a mouse model for another lysosomal disease, MPS II, treatment with HSPC-LVGT expressing iduronate sulfatase (IDS) or epitope tagged IDS (IDS.ApoE2) also resulted in a lack of correlation between IDS enzyme activity in tissue lysates and in clearance of glycosaminoglycans in the brain." (PMID 36284764, 2022).
Multiple sulfatase deficiency (2 papers, 2021 to 2024). "Patients 3 and 4 are considered as Multiple Sulfatases Deficiency (MSD) patients as mutations in IDS and SUMF1 are related to this disease." (PMID 39194544, 2024). "Determination of IDS activity in cultured amniotic fluid cells returned 8% of normal activity and analysis of a second sulfatase was normal, the latter virtually excluding multiple sulfatase deficiency." (PMID 34258136, 2021).
aplastic anemia (1 paper, 2012). Anemia resulting from bone marrow failure (aplastic or hypoplastic bone marrow). "In the our previous study, we also investigated the expression of polymorphisms at G6PD and IDS genes at the RNA level using nonradioactive RT-PCR method in 26 aplastic anemia patients and 35 normal females showed 3/35 (9%) clonallity pattern in normal controls." (PMID 23150832, 2012).
celiac disease (1 paper, 2022). An autoimmune genetic disorder with an unknown pattern of inheritance that primarily affects the digestive tract. "The most significantly up-regulated genes in celiac disease were TAP1, HLA-E, HCP5, STAT1, GBP1, STAT1, LOC100419583, and GBP4 and the down-regulated ones were IDS, PKIB, FBXO2, OXT, and ADI1." (PMID 36011206, 2022).
encephalitis (1 paper, 2025). An acute inflammatory process affecting the brain parenchyma. "In addition, we validated the upregulation of mRNA GUCY1A3, IDS, PARVB, and TROVE2 in anti-NMDAR encephalitis via PCR." (PMID 40948637, 2025).
frontotemporal dementia (1 paper, 2023). Frontotemporal dementia (FTD) comprises a group of neurodegenerative disorders, characterized by progressive changes in behavior, executive dysfunction and language impairment, as a result of degeneration of the medial prefrontal and frontoinsular cortices. "Significant advances were made with anti-TfR1 antibodies as brain shuttles for delivering of iduronate-2-sulfatase (IDS) for mucopolysaccharidosis type II (MPSII), anti-amyloid beta antibody (gantenerumab) for AD and progranulin for frontotemporal dementia, with clinical trials ongoing." (PMID 36986599, 2023).
fungal infection (1 paper, 2022). "To understand the regulation of terpenoid biosynthesis after fungal infection in Norway spruce bark, we followed up on the activation of IDS genes by looking for changes in IDS enzyme activity by assaying crude protein extracts in vitro." (PMID 35599904, 2022).
invasive breast carcinoma (1 paper, 2020). A carcinoma that infiltrates the breast parenchyma. "DNASE1, FUNDC2, and IDS are genes hypermethylated in invasive breast cancer stage, although they demonstrate detectable hypomethylation in ADH and DCIS stages." (PMID 32051475, 2020).
neuroblastoma (1 paper, 2024). Neuroblastoma (NB) is the most common solid, extracranial childhood tumor. "These ID proteins are generally degraded via ubiquitin-proteosome pathway and there is only one report exist in literature suggesting autophagy mediated degradation of IDs in neuroblastoma." (PMID 39123206, 2024).
Ventricular hypertrophy (1 paper, 2022). Enlargement of the cardiac ventricular muscle tissue with increase in the width of the wall of the ventricle and loss of elasticity. "One of them presented a new variant of the IDS gene: c.1563A > T (p.Glu521Asp), hence the comparison with the previous literature was not possible; in addition, the ventricular hypertrophy and the mitral steno-insufficiency were possibly to be ascribed to the late age at diagnosis (44 years)." (PMID 35768874, 2022).
tumor (5 papers, 2024). "This analysis led to the identification of genes generally associated with cancer cells (MUC1, LGALS3, UGDH, TSTA3, and GALE) or the stromal compartment (LGALS1, PSAP, LGALS9, IDS, and MGAT1) in most of the tumor types analyzed." (PMID 38384845, 2024).
cancer (4 papers, 2007 to 2024). A tumor composed of atypical neoplastic, often pleomorphic cells that invade other tissues. "We hypothesized that decreased expression of the enzyme Iduronate-2-sulfatase (IDS) can lead to increased DS levels, which would enhance the invasion of cancer cells." (PMID 31574977, 2019). "In consonance with our hypothesis, the expression levels of DS-degrading enzyme IDS were depleted in all histological types of cancers when examined in the TCGA database and observed to be decreased in invasive malignant epithelia compared with non-invasive or untransformed breast epithelia." (PMID 31574977, 2019). "There is no known association with iduronate 2-sulfatase precursor in cancer research." (PMID 19455237, 2007). "We found that IDS protein was highly expressed in non-cancerous acinar epithelia with very sparse staining in cancer cells within the sections." (PMID 31574977, 2019).
brain disease (1 paper, 2013). "MPS affects CNS; however enzyme replacement therapy is not effective for the brain disease since the therapeutic proteins, such as iduronate-2-sulfatase (IDS) for MPS type II, do not cross the BBB and cannot be delivered to the brain." (PMID 23840214, 2013).
skeletal dysplasia (1 paper, 2021). Any Mendelian diseases that affects growth and development of the skeleton. "Our data here demonstrate the ability of ETV:IDS to reverse skeletal dysplasia in our MPS II mouse model, as treatment was initiated at a stage in disease progression when deficits in bone morphology were already present." (PMID 34622797, 2021).
IDS also shares sentences with these, for which no sentence is quoted: genetic disorder (4 papers); Mucopolysaccharidosis type I (3); breast carcinoma (2); developmental delays (2); fragile X syndrome (2); Hurler-Scheie, Scheie syndrome (2); Intellectual disability (2); Lesch-Nyhan syndrome (2); prostate carcinoma (2); acute myeloid leukemia (1); Alzheimer disease (1); aortic insufficiency (1); autoimmune disease (1); diabetes (1); diabetic nephropathy (1); dysostosis multiplex (1); epilepsy (1); Fabry disease (1); Gaucher disease (1); hemophilia (1); hemophilia A (1); Hernia (1); Hurler syndrome (1); Lissencephaly (1); McLeod syndrome (1); memory impairment (1); Morquio A syndrome (1); Mucopolysaccharidosis I (1); myotubular myopathy (1); Nephropathy (1).
A further 19 diseases each share a sentence with IDS in 1 paper.